APP (amyloid beta precursor protein)
Diseases named in the same sentence as APP in open-access papers (continued):
Sharing a sentence is not in itself a finding about the gene and the disease.
Alzheimer disease (continued). "The amyloid precursor protein (APP) is the parent polypeptide from which amyloid-beta (Aβ) peptides, key etiological agents of Alzheimer’s disease (AD), are generated by sequential proteolytic processing involving β- and γ-secretases." (PMID 31174368, 2019). "Treatment with PLGA-PEG-B6/Cur was led to a decrement in the level of Aß and tau phosphorylation and inhibited the generation of BACE1, APP, and PS1as markers of Alzheimer’s disease." (PMID 31417253, 2019). "The GC of Hippocampus and cortex neurons from APP Swedish mutation and exon deletion mutant of human PS1 transgenic mice (as a model of Alzheimer’s disease) showed swollen cisternae and disorganized stacks." (PMID 31331075, 2019). "The hub gene APP is encoded on HSA21, and the peptides formed from amyloid precursor protein (APP) degradation are the major component of amyloid plaques in Alzheimer’s disease, a frequent complication in DS patients." (PMID 30989628, 2019). "In this study, we report for the first time that the administration of minor ginsenoside F1 rescues memory impairment in APP/PS1 double transgenic mice which are known as Alzheimer’s disease model mice." (PMID 31488185, 2019). "With regard to Alzheimer’s disease (AD) overexpressed amyloid beta precursor protein (AβPP), a substrate for amyloid beta (Aβ) synthesis, was reported to suppress HMGCR." (PMID 30909654, 2019). "It was recently demonstrated that feeding a mouse models of Alzheimer disease (APP/PS1 transgenic mice) with an HFD induced a worsening of insulin and leptin resistance leading to an aggravation of the diabetic state." (PMID 31656993, 2019). "The metalloprotease ADAM10 is a drug target in Alzheimer's disease, where it cleaves the amyloid precursor protein (APP) and lowers amyloid‐beta." (PMID 30833305, 2019). "Complex formation with GBRs stabilizes APP at the cell surface and reduces proteolysis of APP to Aβ, a component of senile plaques in Alzheimer’s disease patients." (PMID 30902970, 2019). "Background and objective: Deregulation of the expression of amyloid precursor protein (APP) can lead to the development of Alzheimer’s disease (AD)." (PMID 30914454, 2019). "While APP is best understood in the context of Alzheimer disease, there is a growing body of evidence suggesting the molecule and its derivatives play a broader role in regulating neuronal hyperexcitability, a well-characterized phenotype in FXS." (PMID 31551722, 2019). "In Alzheimer's disease, as an example, the phosphorylated tau protein forms neurofibrillary tangles and glycosylation defects have been observed in the amyloid precursor protein (APP) and other proteins." (PMID 31131283, 2019). "More specific types of instability (submicroscopic copy number and structure instability of the APP gene) have been discovered to affect the Alzheimer’s disease brain, as well." (PMID 31109140, 2019). "Damage to axonal transport of APP is believed to contribute to the pathogenesis of Alzheimer’s disease." (PMID 31806024, 2019). "Tolfenamic acid is a nonsteroidal anti-inflammatory drug with neuroprotective properties, and it alleviates learning and memory deficits in the APP transgenic mouse model of Alzheimer's disease." (PMID 31049134, 2019). "RELA is involved in TCR-, BCR-, TLR-, and RIG-I-like receptor-signalling pathways, whereas APP is involved in Alzheimer’s disease pathway." (PMID 31666081, 2019). "Here, we address the role of KLC1 serine-460 phosphorylation in APP axonal transport and processing, and in Alzheimer’s disease." (PMID 31806024, 2019). "APP is processed by β- and γ-secretases to produce amyloid-β (Aβ), which is the prominent peptide found in the case of Alzheimer’s disease (AD)." (PMID 31035599, 2019). "We recently demonstrated an endolysosomal accumulation of the β-secretase-derived APP C-terminal fragment (CTF) C99 in brains of Alzheimer disease (AD) mouse models." (PMID 31827783, 2019).
Alzheimer disease (continued). "We subjected double transgenic Alzheimer’s disease (APP/PSEN1) and wild-type mice to mechanical ventilation for 4 h and compared to non-mechanically ventilated Alzheimer’s disease model and wild-type mice." (PMID 30795776, 2019). "BACE1 is the first enzyme involved in APP processing, thus it is a strong therapeutic target candidate for Alzheimer’s disease." (PMID 31882662, 2019). "The role of the Amyloid Precursor Protein (APP) in the pathology of Alzheimer’s disease (AD) has been well studied." (PMID 31354437, 2019). "In the brain of APP/PS1/Ear2(−/−) mice, a transgenic model of Alzheimer’s disease, MRI detected noradrenergic neuron loss in the locus coeruleus." (PMID 30903359, 2019). "The mechanisms that regulate axonal transport of APP are therefore directly relevant to Alzheimer’s disease pathogenesis." (PMID 31806024, 2019). "While the study suggests that APP could be undergoing somatic retro-insertion (which can be mediated by retrotransposons such as L1), it remains unclear if these novel APP variants have a pathogenic role in Alzheimer’s disease, or if they are a by-product of other underlying pathogenic mechanisms." (PMID 31372185, 2019). "The accumulation of amyloid β peptides is relevant to the dysfunction of both APP and γ secretase, and APP/PS1 double knockout mice, which express both mutated human APP and PS1, are used as a model of Alzheimer’s disease." (PMID 31208099, 2019). "The present findings are also consistent with results from patients with Alzheimer's disease (AD) and individuals with familial AD due to genetic mutations in Presenilin 1 or APP (amyloid precursor protein)." (PMID 30069971, 2019). "This is because disruption to anterograde axonal transport of APP is an early feature of Alzheimer’s disease, such disruption promotes amyloidogenic processing of APP and altered processing of APP itself perturbs axonal transport." (PMID 31806024, 2019). "Due to its involvement in Alzheimer’s disease (AD), the amyloid precursor protein (APP) is the most extensively studied γ-secretase substrate." (PMID 30926830, 2019). "The expression of astrocytic sEH in the brains of APPswe/PSEN1dE9 (APP/PS1) mice developing Alzheimer’s disease (AD)-like pathology was evaluated by confocal imaging." (PMID 31176371, 2019). "Here, we report that a minor ginsenoside F1 improves memory function in APPswe/PSEN1dE9 (APP/PS1) double-transgenic Alzheimer’s disease (AD) model mice." (PMID 31488185, 2019). "Human APP and its proteolytic cleavage has been extensively studied due to its relevance in Alzheimer’s disease (AD)." (PMID 31354437, 2019). "Related to Alzheimer’s disease (AD) lentivirus-based RNA silencing of BACE1 attenuated amyloid precursor protein (APP) cleavage and β-amyloid production, which led to reduced neurodegeneration and behavioral deficits in an AD mouse model." (PMID 30832256, 2019). "The amyloid-beta (Aβ) peptide that accumulates in Alzheimer’s disease (AD) is derived from amyloid precursor protein (APP) following proteolysis by β- and γ-secretases." (PMID 31058853, 2019). "Processing of amyloid beta precursor protein (APP) into amyloid-beta peptide (Aβ) by β-secretase and γ-secretase complex is at the heart of the pathogenesis of Alzheimer’s disease (AD)." (PMID 31607898, 2019). "β-site APP-cleaving enzyme 1 (BACE1) initiates amyloid precursor protein (APP) cleavage and β-amyloid (Aβ) production, a critical step in the pathogenesis of Alzheimer’s disease (AD)." (PMID 31108937, 2019). "The presenilin (PS) proteins exert a crucial role in the pathogenesis of Alzheimer disease (AD) by mediating the intramembranous cleavage of amyloid precursor protein (APP) and the generation of amyloid β-protein (Aβ)." (PMID 30823664, 2019). "Cleavage of the amyloid precursor protein’s (APP) transmembrane domain (TMD) by γ-secretase is a crucial step in the aetiology of Alzheimer’s Disease (AD)." (PMID 30926830, 2019).
Alzheimer disease (continued). "APP is a single-pass transmembraneprotein highly expressed in the brain and is a key factor in thedevelopment of Alzheimer's disease." (PMID 29618902, 2018). "Other recent studies using a different mouse genetic model of Alzheimer’s disease [human APP (hAPP) transgenic] reported that these animals develop abnormal electrical activity in the hippocampus." (PMID 29506031, 2018). "Intracerebral injections of beta-amyloid (Aβ) require femtogram quantities of brain-derived Aβ seeds to induce an Alzheimer’s disease (AD)-like pathology in amyloid precursor protein (APP)-transgenic APP23 or tg2576 mice." (PMID 29506560, 2018). "Ultrasound were shot, by a piezoelectric transducer, in the brain of a double transgenic mouse model of Alzheimer’s disease (APP/PS1 ΔE9)." (PMID 30231587, 2018). "Early-onset Alzheimer disease (AD)-like pathology in Down syndrome is commonly attributed to an increased dosage of the amyloid precursor protein (APP) gene." (PMID 29861166, 2018). "In the in vitro model of Alzheimer's disease and in APP/PS1 mice, the administration of TAT‐CAPONi reduced nNOS–CAPON interaction (p < .05)." (PMID 29577585, 2018). "Amyloid precursor protein (APP) and the APP secretase cleavage product beta amyloid are thought to be closely involved in Alzheimer’s disease pathogenesis." (PMID 29587359, 2018). "Presenilins are part of a multi-protein γ-secretase enzyme complex, which mediates the γ-cleavage of amyloid precursor protein (APP) to produce Aβ peptides, a process which is dysregulated in Alzheimer’s disease." (PMID 30070159, 2018). "The central pathological feature of Alzheimer's disease (AD) is the sequential proteolytic processing of amyloid precursor protein (APP) to amyloid-β peptides (Aβ) agglomeration." (PMID 30338033, 2018). "The APP/PS1 mice is a good model for Alzheimer’s disease research and the spatial learning ability is deteriorated." (PMID 30107760, 2018). "The age-dependence of iron accumulation due to APP dysfunction in mice is consistent with both familial and sporadic Alzheimer’s disease as adult onset diseases in humans." (PMID 30150923, 2018). "Mutations in the Amyloid Precursor protein (APP), Presenilin 1 (PSEN1) and Presenilin 2 (PSEN2) genes and duplications of the APP locus are the main causes of autosomal dominant early-onset Alzheimer's disease." (PMID 29875629, 2018). "The resulting transgenic mouse model, Alzheimer’s disease-like pathology with APP, PSEN1, and MAPT transgenes (ADLPAPT), exhibited Aβ accumulation, NFTs, early neuronal loss in the brain, and subsequent memory impairments." (PMID 29338754, 2018). "Possible reasons for leptin’s anti-Alzheimer’s disease effects include its ability, shown in mice, to reduce beta and gamma secretase activity, decrease cleavage of APP and decrease accumulation of beta amyloid." (PMID 29587359, 2018). "A prominent example is the c-Jun NH2-terminal kinase (JNK)-interacting protein 1 (JIP1) that is involved in the anterograde transport of the amyloid precursor protein (APP), a key determinant in Alzheimer’s disease." (PMID 30320553, 2018). "Individuals with trisomy of chromosome 21 possess three copies of the APP gene and show early onset Alzheimer’s disease." (PMID 30150923, 2018). "Here, we completed a preclinical proof-of-concept study in the APP/PS1 murine model of Alzheimer’s disease." (PMID 30283042, 2018). "In the same way, Alzheimer's disease (AD) is characterized by intracellular accumulation of tau protein as well as β-amyloids (Aβ), derived from the amyloid precursor protein (APP)." (PMID 30687233, 2018). "Oligomeric assemblies of neurotoxic amyloid beta (Abeta) peptides generated by proteolytical processing of the amyloid precursor protein (APP) play a key role in the pathogenesis of Alzheimer’s disease (AD)." (PMID 29673150, 2018). "APP is cleaved to produce amyloid beta (Aβ) peptides, which can form plaques in the brain in Alzheimer’s disease." (PMID 29447215, 2018).
Alzheimer disease (continued). "Mutations of the intramembrane protease presenilin (PS) or of its main substrate, the amyloid precursor protein (APP), cause early-onset form of Alzheimer disease." (PMID 30429473, 2018). "This indicates that triplication of chromosome 21 genes other than APP is likely to have an important role to play in Alzheimer’s disease pathogenesis in individuals who have Down syndrome." (PMID 29945247, 2018). "Alzheimer’s disease (AD) is a neurodegenerative condition resulting in part from increased β-secretase cleavage of amyloid precursor protein (APP) and a concomitant increase in amyloid-β (Aβ) over the alternative α-secretase cleavage products." (PMID 29426354, 2018). "Some scholars reported that NGR1 treatment significantly improved cognitive function in the APP/PS1 double-transgenic mouse model of Alzheimer’s disease." (PMID 29696512, 2018). "In the APP/PS1 transgenic mice model of Alzheimer disease, glucose tolerance and insulin sensitivity were impaired 6–7 months prior to amyloid plaque pathogenesis and cognitive dysfunction." (PMID 30153273, 2018). "It was possible to revert this process, which is highly impaired in Alzheimer’s disease, by co-culturing neonatal microglia in brain slices of 20 month-old APP/PS1 mice." (PMID 30382133, 2018). "In this study, we examined the effect of a reduction in yata expression in the Drosophila Alzheimer's disease model, in which expression of human mutant APP was induced." (PMID 30226901, 2018). "Delta-secretase cleaves both APP and Tau to mediate the formation of amyloid plaques and neurofibrillary tangle in Alzheimer’s disease (AD)." (PMID 29725016, 2018). "The processing of amyloid precursor protein (APP) to form the neurotoxic pro-aggregatory Aβ peptide is believed to be a key initiating event in the pathogenesis of Alzheimer’s disease." (PMID 29368044, 2018). "We report here that a single intravenous injection of an Alzheimer disease patient’s-brain extract into APP/PS1 recipient mice led to cerebral amyloid angiopathy within 180 days post injection." (PMID 29506560, 2018). "We previously found that intraperitoneal treatment with S14 exerted neuroprotection in an Alzheimer’s disease (AD) model (in APP/PS1 mice)." (PMID 29458418, 2018). "Certain features related to the third copy of chromosome 21 (which carries the APP gene and several anti-angiogenesis genes) create an environment favorable for Alzheimer’s disease and unfavorable for cancer." (PMID 29587359, 2018). "It is known that dormant inherited mutations in APP, PSEN1, and PSEN2 lead to early onset Alzheimer’s disease (EOAD) and mutations in MAPT, GRN and C9ORF72 cause familial FTD." (PMID 30090657, 2018). "Amyloid beta (Aβ) is formed by cleaving the amyloid precursor protein (APP) by secretases and important pathological changes in the brain of patients with Alzheimer’s disease include increased deposition of Aβ and hyperphosphorylation of Tau protein." (PMID 30262775, 2018). "Here, we report for the first time that triplication of chromosome 21 genes other than APP, increases amyloid-β aggregation, plaque formation, and cognitive deficits in a novel Down syndrome–Alzheimer’s disease (amyloid-β deposition) mouse model." (PMID 29945247, 2018). "Familial Alzheimer’s disease (FAD), due to dominantly inherited mutations in the presenilin 1 (PSEN1), PSEN2, and amyloid precursor protein (APP) genes, accounts for a small proportion (approximately 1%) of all cases of AD." (PMID 29562504, 2018). "Mutations in the APP, PSEN1, and PSEN2 genes cause early onset Alzheimer’s disease (EOAD) that follows a Mendelian inheritance pattern." (PMID 29740579, 2018). "Alzheimer's disease mouse models that overexpress amyloid precursor protein (APP) and presenilin 1 (PS1) form β-amyloid (Aβ) plaques, a hallmark Alzheimer's disease lesion." (PMID 30315100, 2018).
Alzheimer disease (continued). "Hung and Livesey demonstrate that mutations in APP and PSEN1 that are causal for early onset Alzheimer’s disease lead to major defects in lysosome function and autophagy in human neurons." (PMID 30590039, 2018). "For example, amyloid precursor protein (APP) ferroxidase activity couples with surface ferroportin to export iron, but its activity is inhibited in Alzheimer's disease, thereby causing neuronal iron accumulation." (PMID 30383537, 2018). "Treatment of murine primary neuron cultures with amyloid-β (Aβ)-42 peptides, the 42 kDa neurotoxic cleavage product of APP often found in Alzheimer's disease, stimulated ColVI expression via a TGF-β type II receptor-dependent mechanism." (PMID 29728408, 2018). "To determine if trisomy of chromosome 21 sequences other than APP is sufficient to modify Alzheimer’s disease-related phenotypes, we crossed Tc1 mice with the APP transgenic mouse strain Tg(PDGFB-APPSwInd)20Lms (J20-tgAPP)." (PMID 29945247, 2018). "In APP/PS1 transgenic Alzheimer's disease mice, orexin gene knock out markedly decreases the amount of Aβ pathology, while rescue of orexinergic neurons increases the amount of Aβ pathology in the brain." (PMID 30687008, 2018). "In this regard, genomic mosaicism in single, sporadic Alzheimer's disease neurons characterized by an increase in total DNA content and amyloid precursor protein (APP) gene copy number was reported." (PMID 30050570, 2018). "On the other hand, while Alzheimer's disease is a late-onset disease, our model and double APP knock-out mice show developmental defects in synapses." (PMID 30226901, 2018). "Further behavioral studies revealed that activation of neurotensin type 1 receptors enhances spatial learning and therefore improves memory status in APP/PS1 Alzheimer's disease mice model." (PMID 30687008, 2018). "We developed an animal model presenting both Alzheimer’s disease (AD) and type 2 diabetes (T2D), by crossing APP/PS1 mice (AD model) with streptozotocin (STZ)-treated mice (a T2D model)." (PMID 29263141, 2018). "Sequential proteolytic processing of amyloid precursor protein (APP) leads to amyloid-β peptides (Aβ) agglomeration, the central pathological feature of Alzheimer's disease (AD)." (PMID 30338033, 2018). "Aβ peptides, the major components of Alzheimer’s disease (AD) amyloid deposits, are released following sequential cleavages by secretases of its precursor named the amyloid precursor protein (APP)." (PMID 30524243, 2018). "Fluoxetine was administered via intragastric injection to APP/tau/PS1 mouse model of Alzheimer’s disease (3×Tg-AD) mice for 4 months." (PMID 29910725, 2018). "Its enzymatic activity results in secretion of a neuroprotective APP cleavage product (sAPP-alpha) and prevents formation of the amyloidogenic A-beta peptides, major hallmarks of Alzheimer’s disease (AD)." (PMID 29358714, 2018). "Mis-processed APP, (Aβ1-42) its extracellular aggregation is one neuropathological marker used to classify Alzheimer’s disease (AD)." (PMID 30283295, 2018). "Dominantly inherited mutations in amyloid precursor protein (APP), presenilin 1 (PSEN1), and presenilin 2 (PSEN2) cause early-onset Alzheimer disease (AD)." (PMID 30045758, 2018). "Triplication of APP is thought to largely contribute to the onset of Alzheimer’s disease (AD) in people with DS, who tend to develop AD, with a higher prevalence at a much younger age than the euploid population." (PMID 29215943, 2018). "Alzheimer’s disease (AD) is a neurodegenerative disease driven in large part by accumulated deposits in the brain of the amyloid precursor protein (APP) cleavage product amyloid-β peptide (Aβ)." (PMID 29426354, 2018). "APP has been intensely studied with regard to Alzheimer’s disease (AD) pathogenesis, as proteolytic processing of APP gives rise to the Aβ peptide that is deposited in extracellular plaques in the brains of Alzheimer patients." (PMID 28690498, 2017).